SPOP (speckle type BTB/POZ protein)
Diseases named in the same sentence as SPOP in open-access papers (continued):
Sharing a sentence is not in itself a finding about the gene and the disease.
prostate carcinoma (continued). "SPOP (Speckle-type POZ Protein) was one of the most frequently mutated genes in primary prostate cancer, suggesting SPOP is a potential driver of prostate cancer development and progression." (PMID 28448495, 2017). "In contrast, the prostate cancer-associated SPOP mutants (SPOP-Y87N, F125V and F133L) lost the capacity to suppress mitochondrial fission monitored by immunofluorescence." (PMID 28448495, 2017). "Previous studies have shown that SPOP is mutated in many human cancers including prostate cancer, endometrial cancer, colorectal cancer, gastric cancer, and thyroid follicular tumors." (PMID 28599312, 2017). "Cancer is considered to be a genomic disease, and recent studies have identified mutations in speckle-type POZ protein (SPOP) in up to 15% of human primary prostate cancer (PCa) patients." (PMID 28810879, 2017). "Previous study showed that only one copy of SPOP allele is mutated in prostate cancer and SPOP mutants exert their tumor-promoting function in a dominant-negative manner to inhibit the wild-type SPOP." (PMID 28448495, 2017). "Inactivation of SPOP by knockdown or overexpression of prostate cancer-associated SPOP mutants leads to increased prostate cancer cell proliferation, migration and invasion, implying SPOP is a tumor suppressor." (PMID 28448495, 2017). "Although SPOP mutation is now recognized as a distinct molecular feature in a subtype of prostate cancer, the underlying mechanisms remain poorly understood." (PMID 28448495, 2017). "Although somatic mutations in SPOP are rare in most human cancers, they occur at higher rates in EC, and prostate cancer." (PMID 29137450, 2017). "Prostate cancer-associated SPOP mutants lost the capacity to interact with its cytoplasmic binding partner, and localized exclusively in the nucleus." (PMID 28448495, 2017). "In this report, the three most frequent SPOP mutations in prostate cancer, Y87N, F102C, and F133V, were unambiguously confirmed in respective transfected HEK293T cell lines using these PRISM-SRM assays." (PMID 28810879, 2017). "In TCGA database, the highest mutation frequency for SPOP was 7.63% (38/498) in prostate cancer, ZNF148 11.25% (9/80) in uveal melanoma 14.3%) and EZH1 11.25% (9/80) in uveal melanoma." (PMID 28580939, 2017). "Our study, for the first time, links prostate cancer-associated SPOP mutations to mitochondrial dynamics-related cell migration and invasion." (PMID 28448495, 2017). "Speckle-type POZ protein (SPOP), as a cullin-based E3 ubiquitin ligase, has been identified as one of the most frequently mutated genes in prostate cancer (PCa)." (PMID 29262542, 2017). "The linkage of SPOP to cancer was first revealed by cancer genomic analyses, which uncovers SPOP as a significantly mutated gene in human prostate cancers." (PMID 27200299, 2016). "The SPOP–SENP7 axis promotes prostate cancer senescence, which is impaired by the presence of prostate cancer-associated SPOP mutants." (PMID 27200299, 2016). "SPOP functions in DNA double strand break repair and SPOP mutations in prostate cancer are associated with genomic instability." (PMID 27379159, 2016). "Despite gene rearrangements, such as the TMPRSS2-ERG genes fusion, recurrent mutations in the speckle-type POZ (SPOP) gene occur in up to 15% of prostate cancers making SPOP the most commonly affected gene by nonsynonymous point mutations in prostate cancer." (PMID 26863016, 2016). "Recent findings suggest a critical tumor suppressor role of wild-type SPOP that is abrogated by prostate-cancer associated mutations of the gene." (PMID 26863016, 2016). "Further investigation is needed to determine which substrates and related signaling pathways were dysregulated in SPOP mutated endometrial or prostate cancer." (PMID 25766326, 2015).
prostate carcinoma (continued). "In contrast, we focused on the phenotypes observed in human prostate cancers harboring SPOP mutations." (PMID 26374986, 2015). "NCOA3 is also linked to prostate cancer cell proliferation and survival and is a key target of the ubiquitin ligase SPOP [mutated in 6–15% of prostate cancer]." (PMID 25896606, 2015). "Prostate cancers with mutations to a protein called SPOP use an error-prone method to repair broken DNA strands." (PMID 26506153, 2015). "The most commonly mutated gene in prostate cancer encodes Speckle-type POZ protein (SPOP), which is mutated in around 10% of primary prostate tumors." (PMID 26506153, 2015). "SPOP mutations define a distinct molecular class of prostate cancer; they are mutually exclusive with ETS rearrangements but display distinct patterns of somatic copy number alterations (SCNAs)." (PMID 26374986, 2015). "Mutations in SPOP (Speckle-type POZ protein) occur in around 10% of prostate cancers and represent the most common non-synonymous mutations in primary prostate cancer." (PMID 26374986, 2015). "Here, we show that SPOP, the most commonly mutated gene in primary prostate cancer modulates DNA double strand break (DSB) repair, and that SPOP mutation is associated with genomic instability." (PMID 26374986, 2015). "MAR: A patent (US Patent Application No: 2013/0331,279) has been issued to Weill Medical College of Cornell University on SPOP mutations in prostate cancer; is listed as co-inventor." (PMID 26374986, 2015). "Another unexpected finding is that SPOP mutational spectra are entirely different between endometrial and prostate cancer." (PMID 25766326, 2015). "A number of substrates have been reported as deregulated by prostate cancer-derived SPOP mutations, but the relevance of these in vitro findings to human prostate cancers is still unclear." (PMID 26374986, 2015). "CEB: A patent (US Patent Application No: 2013/0331,279) has been issued to Weill Medical College of Cornell University on SPOP mutations in prostate cancer; is listed as co-inventor." (PMID 26374986, 2015). "Independent analysis of SCNAs from three publicly available data sets comprising 430 tumors, including 47 SPOP mutant prostate cancers, confirmed that the rearrangement-associated deletions were those enriched in SPOP mutant prostate cancer." (PMID 26374986, 2015). "SPOP mutation frequently co-occurs with specific SCNAs, designating a molecular class of prostate cancer." (PMID 26374986, 2015). "Together, these data nominate a distinct prostate cancer class characterized by early SPOP mutations and genomic instability." (PMID 26374986, 2015). "In contrast, enzalutamide failed to enhance AR downregulation in C4-2 cells expressing the prostate-cancer-associated SPOP mutant F133V." (PMID 24508459, 2014). "This study identifies AR as a bona fide substrate of SPOP and elucidates a role of SPOP mutations in prostate cancer, thus implying the importance of this pathway in resistance to antiandrogen therapy of prostate cancer." (PMID 24508459, 2014). "Given the importance of AR in prostate cancer initiation, progression, and therapy resistance, identification of AR as a substrate of SPOP E3 ligase provides a plausible explanation for the high frequency of SPOP mutations in prostate cancer." (PMID 24508459, 2014). "Recurrent SPOP mutations in prostate cancer have been confirmed by three independent genome-wide studies." (PMID 24508459, 2014). "In the present study, we provide evidence that all of the known prostate-cancer-associated mutants of SPOP lose their ability to bind to and promote AR ubiquitination and proteasome degradation." (PMID 24508459, 2014). "A large-scale somatic mutation study demonstrated that in approximately 450 tumors, comprising breast, lung, ovarian, pancreatic, and prostate cancer, the SPOP gene was highly mutated in prostate cancer." (PMID 24508459, 2014).
prostate carcinoma (continued). "All SPOP mutations detected thus far in prostate cancer occur in the structurally defined substrate-binding motif, suggesting that the pathophysiology of SPOP mutations in prostate cancer is relevant to its function in substrate binding and degradation." (PMID 24508459, 2014). "Mutations in the SPOP gene have been identified in various cancers, including prostate cancer." (PMID 40432836, 2025). "The study suggests that factors regulating GLI3 expression and activity could significantly impact the development and progression of prostate cancer, particularly in the context of SPOP mutations." (PMID 40432836, 2025). "However, it have been shown that prostate cancer-associated SPOP mutations result in aberrant activation of the MAPK/ERK pathway in a BRAF-dependent manner, potentially contributing to the malignant transformation of cancer cells." (PMID 40492122, 2025). "By unraveling the complex interplay between SPOP mutations and the AR signaling pathway, we aim to contribute to the ongoing efforts to improve our understanding of prostate cancer biology and enhance patient outcomes through more precise and effective therapeutic interventions." (PMID 40432836, 2025). "In addition, this study uses computational approaches and data from the TCGA cBioPortal database to explore the landscape of SPOP mutations in prostate cancer." (PMID 40432836, 2025). "Some studies suggest that SPOP-mutated prostate cancers may have distinct responses to ADT, which could influence clinical outcomes." (PMID 40432836, 2025). "The clinical implications of SPOP mutations in prostate cancer are multifaceted." (PMID 40432836, 2025). "Prostate cancer exhibits even more pronounced racial variations: Black men show higher frequencies of SPOP and ZFHX3 mutations but lower rates of TMPRSS2‐ERG fusions and PTEN deletions compared to White men, while Asian men demonstrate increased FOXA1 mutations and fewer PTEN alterations." (PMID 41187942, 2025). "Clinical studies showed that SPOP mutations are present in up to 15% of prostate cancer cases." (PMID 39540935, 2024). "In addition, the protein abundance of CDC20 was negatively regulated by Cullin3SPOP complex, with SPOP being one of the most frequently mutated genes in prostate cancer." (PMID 37528490, 2023). "Moreover, SPOP mutation is a common mutation pattern in prostate cancer, accounting for about 15% of primary prostate cancers." (PMID 36983244, 2023). "Importantly, the AKT regulator PDK1 is stabilized by the E3 ligase speckle-type POZ protein (SPOP), which is mutated in about 15% of early and late-stage prostate cancer." (PMID 36768610, 2023). "It has been previously reported that TOP2A accumulation is induced by SPOP mutation and contributes to prostate cancer progression from the accumulation of DNA damage, and etoposide could be effective for SPOP mutation prostate cancer." (PMID 37240308, 2023). "Interestingly, the frequency of SPOP mutations was significantly higher in primary prostate cancers than in metastatic prostate cancers." (PMID 36983244, 2023). "SPOP mutations are observed predominantly in prostate cancer." (PMID 37705755, 2023). "All twelve prostate cancers with SPOP mutations clustered in the MuAt feature UMAP." (PMID 37420249, 2023). "Moreover, mutations accumulate in SPOP target recognition domains in endometrial and prostate cancers, altering their sensitivity to BET inhibitor therapy." (PMID 37622993, 2023). "Hence, the inability of mutated SPOP to interact with ERG leads to full-length ERG accumulation in prostate cancer." (PMID 35954292, 2022).
prostate carcinoma (continued). "The most strikingly consistent dissimilarities may be the lower frequencies of TMPRSS2-ERG rearrangements, PTEN deletions, and SPOP mutations in prostate cancers from Black men." (PMID 35104804, 2022). "A handful of genes other than SPOP may be mutated more frequently in prostate cancers from Black men." (PMID 35104804, 2022). "Moreover, one of the most frequently mutated E3 ubiquitin ligases in prostate cancer, SPOP, reportedly promotes ubiquitination-mediated proteasomal degradation of AR." (PMID 35203681, 2022). "In addition, mutations of the speckle type BTB/POZ protein SPOP, observed in about 10% of localized primary prostate cancers, have also been shown to drive the development of an oncogenic AR cistrome." (PMID 36212399, 2022). "Importantly, it should be mentioned that ERG fusions and SPOP mutations are mutually exclusive in prostate cancer and manifest common gene signatures, highlighting the potentially redundant role of these two genomic events." (PMID 35954292, 2022). "SPOP is the most commonly mutated gene in primary prostate cancer." (PMID 35975235, 2022). "Notably, SPOP mutations have been linked to genomic instability promoted through the DDR pathway in prostate cancer." (PMID 35954292, 2022). "Interestingly, it was recently shown that prostate cancer cells harboring SPOP mutations are sensitive to ADT, an observation which warrants further investigation." (PMID 35954292, 2022). "In addition, SPOP gene mutation is the most common missense point mutation in prostate cancer and affects the progression of prostate tumours through coordinated regulation of the PI3K/mTOR and AR signalling pathways." (PMID 36474188, 2022). "SPOP is most frequently mutated in prostate cancer, and across 21 various types of cancers." (PMID 34235141, 2021). "Therefore, prostate cancer-associated SPOP mutation F133V impairs DNA re-replication checkpoint, promotes chromosomal instability, and leads to replication catastrophe when ATR is inhibited." (PMID 34599168, 2021). "More importantly, given the critical oncogenic role of HnRNPK and the high frequency of SPOP mutations in prostate cancer, our results provide a molecular rationale for the clinical investigation of novel strategies to combat prostate cancer based on SPOP genetic status." (PMID 34857003, 2021). "This presents a potential mechanism for the physiological regulation of PDK1 turnover by E3 ligase SPOP, and further dictate the pathological conditions of prostate cancer, where patients conceived SPOP mutations, or PDK1 degron-associated mutations facilitate tumorigenesis by activating AKT kinase." (PMID 34353330, 2021). "Interestingly, a multivariate analysis revealed the presence of SPOP mutations as an independent predictor of prostate cancer metastasis." (PMID 34322378, 2021). "Interestingly, all SPOP somatic mutations identified in prostate cancer are clustered in its substrate binding MATH domain, thus having a dominant-negative effect on substrate binding and degradation." (PMID 34630112, 2021). "Notably, almost all SPOP mutations detected thus far (except one mutant) in prostate cancer patients are hemizygous mutations." (PMID 34599168, 2021). "Thus, our findings shed new light on the development of new therapeutics for patients with SPOP-mutated prostate cancer." (PMID 34599168, 2021). "G3BP1high occurs in both wild type and SPOP-mutated prostate cancers." (PMID 34795264, 2021). "Additionally, prostate cancer-associated SPOP mutants inhibit substrate ubiquitination by interfering with the LLPS process." (PMID 34235141, 2021). "Mutations in SPOP are considered the most common recurrent point mutations in prostate cancer." (PMID 33632199, 2021). "Furthermore, we showed that in vitro Geminin poly-ubiquitination by SPOP was abolished in the context of SPOP F102C and F133V, two SPOP mutations most frequently found in prostate cancer patient specimens." (PMID 34599168, 2021).
prostate carcinoma (continued). "TMPRSS2-ERG gene fusions are the most common form of ETS gene family member fusions in prostate cancer and are mutually exclusive with other ETS family member fusions and a number of other somatic molecular alterations in prostate cancer, such as SPOP mutations or SPINK overexpression." (PMID 34191807, 2021). "Moreover, prostate cancer-associated SPOP mutants fail to interact with and promote the destruction of HnRNPK proteins." (PMID 34857003, 2021). "Interestingly, deletion of CHD1, deletion of SPOPL and mutation of SPOP tend to co-occur in prostate cancer tumours." (PMID 32365491, 2020). "CHOP seems to be involved in the progression of prostate cancer associated with SPOP mutations." (PMID 32560326, 2020). "SPOP is rendered ineffective in prostate cancer by genomic mutations promoting cancer." (PMID 33158056, 2020). "Thus, the heterogeneous expression of the prostate cancer-associated SPOP mutants reduced the polyubiquitination of substrates, followed by the inhibition of their proteasomal degradation." (PMID 33023230, 2020). "However, mutation of SPOP, which is frequently observed in prostate cancer and other cancers, disrupted SPOP–substrate co-localization and phase separation, thus reducing ubiquitylation and proteasomal degradation of proto-oncogenic proteins." (PMID 32941624, 2020). "To examine the effect of SPOP mutations on Caprin1 protein levels in prostate cancer specimens from patients, we analyzed Caprin1 protein levels by immunohistochemistry (IHC) methods in a cohort for which a total of 131 primary prostate tumor samples were available." (PMID 31771591, 2019). "SG assembly is aberrantly elevated in SPOP-mutated prostate cancer." (PMID 31771591, 2019). "According to a study about SPOP mutation frequency in prostate cancer across demographically diverse patient cohorts, the most frequently mutated residue was F133 (50%) followed by Y87 (15%), W131 and F102 (9%), F125 (3%), and K129, F104, and K135 (2%), other mutated residues are less frequent." (PMID 31771591, 2019). "Our study reveals that SPOP mutations augment Caprin1-mediated SG assembly and render prostate cancer cells resistance to docetaxel, suggesting that targeting the SG assembly pathway represents a viable strategy to restore docetaxel sensitivity in prostate cancer cells." (PMID 31771591, 2019). "A significant proportion of CHD1-deleted prostate cancers coexpress SPOP mutations." (PMID 31366128, 2019). "We explored whether Caprin1 is an authentic SPOP substrate, and whether its physiological function is dysregulated in SPOP-mutated prostate cancer." (PMID 31771591, 2019). "In fact, both these studies showed that WT SPOP suppresses stem cell tracts promoting Nanog poly-ubiquitination; SPOP mutations determine a loss of this important activity, increasing Nanog levels and determining increased cancer stem cell traits of prostate cancers." (PMID 31366128, 2019). "Increased Caprin1 expression correlates with SPOP mutation status in prostate cancer specimens." (PMID 31771591, 2019). "We postulated that prostate cancer-associated mutants of SPOP may be defective in mediating Caprin1 destruction." (PMID 31771591, 2019). "Moreover, expression of SPOP-WT or the ΔNLS mutant significantly increased stress-induced cell death, while expression of prostate cancer-associated SPOP mutants (F125 V, F133 L) or knockout of endogenous SPOP by shRNAs suppressed stress-induced cell death." (PMID 31771591, 2019). "The SPOP gene is the most frequently mutated gene in primary prostate cancer." (PMID 31771591, 2019). "As above reported, the SPOP gene is frequently mutated in prostate cancer (6–15% of cases)." (PMID 31366128, 2019). "The identification of additional SPOP substrates may help to elucidate the underlying molecular mechanisms of SPOP-mutated prostate cancer." (PMID 29996942, 2018).